RNU6-1177P (RNA, U6 small nuclear 1177, pseudogene)
Gene: Small nuclear RNA gene on chromosome 1 (61,852,499 to 61,852,602, forward strand). Ensembl gene ENSG00000212360.
Homologues: Orthologues: chimpanzee U6 (98% identical), macaque U6 (88% identical), dog U6 (74% identical). Paralogues in human: RNU6-45P (85% identical), RNU6-675P (85% identical), RNU6-562P (84% identical), RNU6-820P (84% identical), RNU6-1152P (83% identical), RNU6-19P (83% identical), RNU6-35P (83% identical), RNU6-1119P (82% identical), RNU6-12P (82% identical), RNU6-13P (82% identical), RNU6-16P (82% identical), RNU6-203P (82% identical), and 1285 more.